CTNNB1 (catenin beta 1)
Diseases named in the same sentence as CTNNB1 in open-access papers (continued):
Sharing a sentence is not in itself a finding about the gene and the disease.
cancer (continued). "In conclusion, the three CTNNB1 SNPs were suggested to have the potential to be novel biomarkers for risk prediction of cancer in overall population or some specific subgroups." (PMID 28963373, 2017). "Alterations in gene expression of CTNNB1 which encodes beta-catenin, have been reported in numerous cancers such as breast colorectal, melanoma, prostate and lung tumors." (PMID 28405929, 2017). "With in-depth basic investigation of CTNNB1 SNPs, accumulating studies have focused on the association between them and the susceptibility to cancer." (PMID 28963373, 2017). "We mapped variant peptides back onto the canonical reference sequence for the oncogene beta-catenin (CTNNB1), revealing several mutations in both the deep and shallow proteomes in cell-lines derived from different cancers." (PMID 28716134, 2017). "Based on that, available data were used to perform a meta-analysis, aiming to explore the association of CTNNB1 polymorphisms with cancer and to provide research clues for screening novel biomarkers for cancer risk prediction." (PMID 28963373, 2017). "This suggested that mutation prevalences are too low to explain many clinical observations of cancer cell detachment from a primary carcinoma even if all ambiguous genotyping results were classed as positive for a CTNNB1 mutation." (PMID 29156750, 2017). "A meta-analysis was performed for the association between four highly studied CTNNB1 SNPs and cancer risk, including rs1798802 A/G, rs4135385 A/G, rs11564475 A/G, and rs2293303 C/T." (PMID 28963373, 2017). "It is phosphorylated and destabilized by CK1 and GSK3B, with stabilized CTNNB1 reported as a hallmark of many cancers." (PMID 28174229, 2017). "In this article, we conducted a systematic review for the researches related to the association of single nucleotide polymorphisms (SNPs) in CTNNB1 with overall cancer risk." (PMID 28963373, 2017). "Recently, Sousa and colleagues analyzed three cases of CCOT using the same cancer hot spot panel we used, and discovered a CTNNB1 Ser33Phe mutation in two cases." (PMID 28658279, 2017). "As with CDH1, for every site the SEER proportion of patients diagnosed with regional or distant disease exceeded our observed prevalence of primary carcinomas with at least one CTNNB1 mutation." (PMID 29156750, 2017). "In the sensitivity analysis, the mutation prevalence of primary carcinomas with at least one CTNNB1 mutation rose to between 5–10% for 8 anatomic sites and between 10–15% for 3 sites." (PMID 29156750, 2017). "Previous studies have shown that gain-of-function mutations in the CTNNB1 gene contribute to the occurrence and development of a variety of carcinomas in humans." (PMID 28514307, 2017). "Specifically, we examined somatic mutations in CDH1 and CTNNB1 in thousands of clinical primary carcinomas from 13 anatomic sites." (PMID 29156750, 2017). "If mutations induce cancer cells to detach from the primary tumor, then one would expect the prevalence of primary carcinomas with a CDH1 or CTNNB1 mutation to be greatest for anatomic sites that are most likely to metastasize." (PMID 29156750, 2017). "There are several lines of evidence showing the contribution of CTNNB1 rs2293303 C > T polymorphism to the risk and prognosis of cancer, elucitating its potential involvment the pathogenesis of human diseases." (PMID 27391264, 2016). "Sample P61 showed a CTNNB1 mutation that has been reported to cause the same accumulation leading to cancer." (PMID 26442106, 2015). "We genotyped 12 haplotype-tagging single nucleotide polymorphisms (htSNPs) in CDH1 and CTNNB1 among 1,160 BC cases and 1,336 age-matched cancer-free controls using the TaqMan® Genotyping Assay." (PMID 26285011, 2015).
cancer (continued). "Consistent with its known cytoplasmic roles, hnRNPA2 was associated with 3′-UTR mRNAs of several cancer-relevant mRNAs including β-catenin (CTNNB1)." (PMID 24823909, 2014). "CTNNB1 mRNA levels can modulate Wnt signalling, and Wnt activity has been linked to cancer stemness in the colon." (PMID 22970250, 2012). "β-Catenin (encoded by CTNNB1) is an important component of intercellular junctions, such as the components of adherens junctions, and its aberrant expression has been associated with many malignant neoplasms." (PMID 40699660, 2025). "Hyperactivation of the Wnt/beta-catenin pathway may confer resistance to inhibitors of PI3K and Akt, and cancers with CTNNB1 mutations are presumed to be resistant also to pharmacologic inhibition of upstream components of the WNT pathway." (PMID 40843798, 2025). "It was demonstrated that CTNNB1 is a key factor in the interaction of the canonical Wnt signaling pathway with 10 upregulated cancer-associated genes, which reveals efficient biomarkers that can be used for the prognosis of cancers." (PMID 40804837, 2025). "Additionally, we observed a positive correlation (Pearson correlation coefficient = 0.45; n = 18) between the reduction in cancer cell viability induced by sorafenib treatment and that caused by CTNNB1 knockout." (PMID 40293950, 2025). "However, mutations in CTNNB1 disrupt these normal regulatory processes, leading to aberrant activation of the Wnt/β-catenin pathway and contributing to cancer development." (PMID 40072110, 2025). "We found that compared to CTNNB1 WT carcinomas, samples harboring CTNNB1 mutations showed significantly decreased levels of IL1A (p-value = 0.045), IL1B (p-value = 0.12), and caspase 1 (p-value = 0.037), while demonstrating similar IL1R1 and IL1R2 expression levels." (PMID 41227323, 2025). "This suggests that the CTNNB1 mutation status could serve as a prognostic marker for a higher post-operative recurrence in these cancers." (PMID 37347751, 2023). "We also built a multi-miRNA expression model for CTNNB1 mutated cancers, with an AUC of 0.78." (PMID 37958433, 2023). "We, therefore, must assume that APC/CTNNB1 somatic mutations may have differential effects in cancer cells other than by merely activating β-catenin." (PMID 34986841, 2022). "CTNNB1 mutations can be found in difficult-to-classify tumors with deep penetrating morphology and additional molecular and methylation analysis can help differentiate between benign and malignant tumors in these cases." (PMID 36077603, 2022). "We discovered that CTNNB1 also harbored IDR mutation hotspots that merged with pan-cancer." (PMID 35061901, 2022). "Cancer-causing mutations in CTNNB1 are mostly somatic, gain-of-function mutations." (PMID 35935366, 2022). "Previous studies have found the association of CTNNB1 mutations with several cancers." (PMID 35053583, 2022). "Only approximately 3% of malignant neoplasms harbor CTNNB1 mutations." (PMID 36428715, 2022). "In this setting, CTNNB1 somatic mutations associated with MMR deficiency may possibly act as driver events for LS cancer progression." (PMID 33923068, 2021). "This, together with the rather low prevalence of CTNNB1 mutations among MLH1-associated incident cancers, could indicate that the progression with immediate invasive growth was not dominant in the analyzed set of incident cancers." (PMID 34206061, 2021). "Somatic mutations in the CTNNB1 gene have been identified in many types of cancer." (PMID 33237662, 2021).
cancer (continued). "Increasing studies indicate that somatic mutations within the exon 3 of CTNNB1 usually stabilize β-catenin protein and activate Wnt signaling pathway in cancers, but the biological function of this novel CTNNB1 mutations in ACP remains unknown." (PMID 34922552, 2021). "All MSI-H cancers displayed CTNNB1 mutations affecting either residue T41 or S45." (PMID 33115416, 2020). "In conclusion, this study shows that in contrast to extracolonic cancers stabilizing CTNNB1 mutations in CRC are commonly homo- or hemizygous indicating a higher threshold of β-catenin stabilization to be required for transformation in the colon as compared to extracolonic sites." (PMID 33115416, 2020). "It is estimated that at least 10% of cancer samples sequenced have exhibited mutation in CTNNB1." (PMID 33076339, 2020). "Mutations in the gene CTNNB1 that encodes β-catenin have resulted in cancer." (PMID 33076339, 2020). "However, the aberrant activation or mutation in CTNNB1 is associated with several diseases as well as cancers, such as colon cancer, pancreatic cancer, lung cancer, ovarian cancer, hepatoblastoma, and thymoma." (PMID 33029148, 2020). "As regards CTNNB1, the very modest rate of 14% mutations in our cohort and 16% across all ACCs is notably higher than in many cancers and may suggest a putative role in a subset of ACCs." (PMID 33148256, 2020). "The CTNNB1 gene causes cancer, and mutated CTNNB1 was distributed in both high and low TS scores." (PMID 33072579, 2020). "We identify scFvs specifically targeting the β-catenin neoantigen that could serve as building blocks for the development of antibody-based therapies for cancers harboring CTNNB1 mutations." (PMID 31690625, 2019). "Such derivatives could be adapted into either cell-based (CAR-T) or protein-based (bispecific T-cell engagers) therapies to target cancer cells harboring the S45F mutation in CTNNB1." (PMID 31690625, 2019). "Interestingly, four of the reported SNPs in the CTNNB1 gene are associated with a higher cancer risk and only one with a reduced risk." (PMID 31248166, 2019). "Previous studies find CTNNB1 mutation related to several cancers." (PMID 30929091, 2019). "Indeed, CTNNB1 has been shown to have altered splice variants expressed in different stages of cancer tissue, although the significance is still under investigation." (PMID 29362363, 2018). "The aim of this review is to discuss PI3K/AKT, Wnt-CTNNB1, and NF-κB signaling pathways, the occurrence of genetic alterations in them, the association of these aberrations with different human cancers and how different nodes of these pathways are targeted by various substances of mushroom origin." (PMID 29094602, 2018). "CTNNB1, the gene encoding for β catenin, is overexpressed in several cancers." (PMID 30366467, 2018). "Paul Polakis (2000) has summarized CTNNB1 mutation spots and rates in human cancers in detail." (PMID 29435196, 2018). "Mutations of the CTNNB1 gene that encodes β-catenin occur in a wide spectrum of cancers." (PMID 29435196, 2018). "It is well accepted that genetic variations influencing the expression and/or function of CTNNB1 might be related to the susceptibility to cancer." (PMID 28963373, 2017). "It has been reported that CTNNB1 polymorphisms are associated with cancer risk." (PMID 28963373, 2017). "Though based on a different set of tumors than the Profile data, the SEER data provide an indirect comparison between our observed prevalences of primary carcinomas with a CDH1 or CTNNB1 mutation and proportions of cases diagnosed with some evidence of cancer cell detachment from the primary tumor." (PMID 29156750, 2017).
cancer (continued). "We hypothesize that if mutations in genes related to EMT, such as CDH1 or CTNNB1, cause a substantial number of cancer cells to detach from a primary tumor, many or most patients with regional or distant disease would have mutations in EMT genes." (PMID 29156750, 2017). "Of them, only CTNNB1 was catalogued in the COSMIC cancer Gene Census, suggesting that the CTNNB1 mutation might be a driver." (PMID 29190888, 2017). "In addition, the study about the association of CTNNB1 polymorphisms with cancer risk remains a relatively emerging field; consequently, the relevant researches are lacking." (PMID 28963373, 2017). "The role of CDH1 or CTNNB1 mutations in generating metastases could potentially vary by carcinoma subtypes within an anatomic site, but such a finer-grained consideration was beyond the scope of the present analysis." (PMID 29156750, 2017). "Nevertheless, across sites, the SEER distributions broadly resemble our available Profile stage data in that the proportions of patients displaying evidence of detachment at diagnosis tend to be much greater than our observed CDH1 or CTNNB1 mutation prevalences in primary carcinomas." (PMID 29156750, 2017). "In conclusion, mutations in TERT promoter and in CTNNB1 gene represent specific cancer signatures in the pathogenesis of viral related HCC and could be promising early biomarkers as well as targets for tailored therapies." (PMID 27276713, 2016). "Our data suggested co-expression of CDH1 and CTNNB1 in the cell membrane might be needed for cell stability because cell instability often causes malignant change of the cancer cell." (PMID 27600761, 2016). "Mutations in CTNNB1 are considered to be cancer drivers for HCC development." (PMID 27010638, 2016). "Correlation of drug activities with cancer gene mutations revealed novel drug sensitivity markers, suggesting that cancers dependent on mutant CTNNB1 will respond to trametinib and other MEK inhibitors, and cancers dependent on SMAD4 to small molecule EGFR inhibitor drugs." (PMID 24651269, 2014). "Data from other cancer types suggest that activating mutations of CTNNB1 that prevent its downregulation may be a more common event than methylation." (PMID 22645611, 2012). "According to several studies, the KRAS mutation accounted for approximately 50%, the PTEN mutation for 35%, and the CTNNB1 mutation for 12%.5,14,15 In some patients, cancer genomic profiling tests may reveal mutations, being useful for selecting a treatment method." (PMID 39896229, 2025). "However, CTNNB1 is positively associated with cancer stemness." (PMID 36123378, 2022). "The pivotal protein β-catenin (gene symbol: CTNNB1) showed an elevated (~two-fold) expression, and as a subunit of the cadherin protein complex that acts as an intracellular signal transducer, mutations and increased expression of β-catenin are associated with many cancers." (PMID 36248973, 2022). "We successfully designed a DNA primer pair appropriate for amplification of the feline CTNNB1 gene exon 2, which is homologous to the nucleotide sequence of human CTNNB1 exon 3 and contains a hotspot region of frequent mutations for various human cancers including CRC." (PMID 34885050, 2021). "Therefore, we analyzed the E-cadherin expression in 17 MSI-H CRCs with known CTNNB1 mutational status (10 homo- or hemizygous, 2 heterozygous, 5 wildtype) Strong reduction of E- Cadherin was found in 11 cancers while 6 CRCs displayed an expression similar to that in surrounding epithelium." (PMID 33115416, 2020). "Furthermore, in this review, we discuss in some detail PI3K/AKT, Wnt-CTNNB1, and NF-κB signaling pathways, the occurrence of genetic alterations in them, the association of these genetic alterations in human cancers and how different nodes of these pathways are targeted by mushroom origin compounds." (PMID 29094602, 2018). "This suggests that increasing metastasis may be associated with CTNNB1 in some cancers." (PMID 19835603, 2009).
cancer (continued). "Functional interrogation demonstrates that cap-proximal m6Am deposition on CTNNB1 increases β-catenin protein expression, promoting cell proliferation, clonogenicity, and migration in cancer cell models." (PMID 41824765, 2026). "Cellular localization of KLF4 and CTNNB1 protein expression in cytoplasm and nucleus with morphological changes of the cancer cells revealed the onset of programmed cell death." (PMID 42224286, 2026). "We first tested two aggressive models to study cancer formation in the context of oncogenic drivers by using CTNNB1/MYC and NRASG12V/shp53 mouse models of HCC." (PMID 40704506, 2025). "Aberrant PIWIL2 expression has been implicated in promoting proliferation in HCC and other cancers, with its tumorigenic functions mediated through interactions with HDAC3, NME2, β-catenin (CTNNB1), and others via the PIWI and MID domains." (PMID 41422314, 2025). "This event has previously been reported as being very frequently dysregulated in cancer, furthermore, preventing inclusion of the intron reduced CTNNB1 levels." (PMID 40684264, 2025). "Mechanically, TFAP2C positively regulates CTNNB1 transcription via binding to the CTNNB1 promoter in cancer cells." (PMID 40837414, 2025). "WNT signaling orchestrates key developmental and homeostatic events; however, its aberrant activation, often driven by mutations in APC, CTNNB1, or AXIN, significantly contributes to the development of cancer." (PMID 40874062, 2025). "CTNNB1 is important for regulation of stem cell pluripotency, cancer signaling, and functions as an epithelial-mesenchymal transition-related gene." (PMID 40676219, 2025). "Cancer cells, identified by the expression of Ctnnb1 and Cdk4, were further stratified into four subtypes (cancer cells 1–4)." (PMID 40723284, 2025). "Surveying 829 polyclonal gastric microbiopsies by targeted sequencing, we find somatic 'driver' mutations in a distinctive repertoire of known cancer genes, including ARID1A, ARID1B, ARID2, CTNNB1 and KDM6A." (PMID 40108450, 2025). "For example, EAS-specific unambiguous probes (n = 484) from the HM450K array were overlapped with promoters and gene bodies of 140 cancer driver genes, such as CTNNB1, DSP, FRK, HLA-A, NOX4, and TRIO." (PMID 40445831, 2025). "In general, CTNNB1 is majorly involved in the Wnt/β-catenin pathway whose activation is well established to contribute to cancer." (PMID 41186627, 2025). "Among the cancer-associated proteins we found five hotspot mutations conferring loss (NFE2L2 E79V/Q) or gain (PMS2 R107W, MUTYH S321L, CTNNB1 S33F) of interactions (Dataset EV6)." (PMID 39009827, 2024). "In contrast, genes such as APC, KRAS, CTNNB1, and GATA6, showed a higher mutation frequency in precancerous lesions than in advanced cancer." (PMID 39554798, 2024).